MIF (macrophage migration inhibitory factor)
Diseases named in the same sentence as MIF in open-access papers (continued):
Sharing a sentence is not in itself a finding about the gene and the disease.
tumor (continued). "Furthermore, the macrophage migration inhibitory factor (MIF) is known to enable tumor macrophages to be polarized to an immunosuppressive and thus pro-tumorigenic phenotype." (PMID 36157879, 2022). "Furthermore, MIF promotes tumor proliferation, migration, invasion, angiogenesis and chemotherapy resistance via binding to different receptors, including CD74, C-X-C motif chemokine receptor 2 (CXCR2), CXCR4, and CXCR7." (PMID 35842634, 2022). "We present a theoretical model based on the hypothesis that highly expressed MIF in tumors and stroma induce MSCs homing to tumors, which are subsequently educated by tumor cells and TME to differentiate into TA-MSCs." (PMID 35842634, 2022). "In addition, tumor cells induced the expression of MIF expression to increase monocytic MDSCs within the tumor, which in turn promoted tumor growth and metastasis in a 4T1 syngenetic mouse model." (PMID 35267547, 2022). "Admittedly, we did not confirm association between tumor size and MIF deregulation, however we highlighted its role in tumor growth." (PMID 34157052, 2021). "This suggests that EBV may promote MIF production in the tumor nest, affecting the progression of NPC." (PMID 34407796, 2021). "Our study exhibited that nuclear MIF expression is a strong predictor of lymph node metastasis, therefore MIF may act as a mediator, modulated to accelerate the tumor progression to its aggressive state." (PMID 34157052, 2021). "Translocation of MIF from cytoplasm to the nucleus may play a critical role in PCa progression and seems to be important for tumor cell growth and invasion." (PMID 34157052, 2021). "MIF is secreted upon inflammatory and stress stimulation by immune, parenchymal and tumor cells." (PMID 34157052, 2021). "Consistent with in vitro findings above, MIF deletion robustly impaired tumor growth in mice." (PMID 34012010, 2021). "MIF downstream signaling proteins in primary tumor cells were detected by western blotting." (PMID 34389619, 2021). "Macrophage migration inhibitory factor (MIF), which was originally discovered as a secreted proinflammatory cytokine with a central role in immune and inflammatory responses, has also been identified as a tumor promoter." (PMID 33542244, 2021). "This proved that MIF promoted tumor metastasis by inhibiting ferroptosis in macrophages." (PMID 35036405, 2021). "Indeed, since tumor suppressor miR-451 downregulates macrophage migration inhibitory factor (MIF) and multi-drug resistance 1 (MDR1), the malignant parental cells selectively release it in body fluids." (PMID 34440329, 2021). "Because of the tumor-specific Hsp90-mediated stabilization of MIF, this protein could be selectively targeted in CRC." (PMID 33542244, 2021). "Thus, in established tumors, stabilized MIF preferentially supports tumor-specific macrophage infiltration, vessel formation, and tumor cell proliferation." (PMID 33542244, 2021). "Also, in PCa with infiltration both right and left area of the gland, we revealed a significant increase in the cytoplasm-located MIF (p = 0.011) and nuclear-located MIF (p = 0.044), than in samples where tumor infiltrate only one side of the gland." (PMID 34157052, 2021). "The addition of stromal cells increased transcription of matrix remodelling proteins FN1 and MMP9, induced release of tumour-promoting immune molecules MIF, Serpin E1, CXCL1, IL-8 and CXCL12 and altered cancer cell expression of immunotherapeutic targets EGFR, CD47 and PD-L1." (PMID 34885111, 2021). "To clarify whether elevated MIF expression in tumor cells mediates tumor-specific macrophage recruitment, we monitored the adjacent epithelium." (PMID 33542244, 2021). "Further, we define a dual role for MIF in CRC tumor progression." (PMID 33542244, 2021).
tumor (continued). "Considering that MIF staining in tumors from patients could also be contributed by stromal/hematopoietic cells, it was plausible that the cooperation or synergism between tumor-secreted MIF and microenvironment MIF could fuel tumor progression and metastasis." (PMID 35036405, 2021). "Based on these prior studies and the inverse correlation of MIF and CD74 in our tumor model, we propose that MIF functions in medulloblastoma to bias myeloid cells toward an Igf1+ phenotype, and acts more effectively in G-Smo tumors, which have higher Mif expression." (PMID 34021242, 2021). "In conclusion, our data showed that rSmeg-hMIF-hIL-7 exerts a strong antitumor immune response in mice, possibly by inhibiting the MIF-dependent promotion of tumorigenesis by the anti-MIF immune response and via enhanced cytotoxic T cell recruitment into tumor microenvironments." (PMID 34389619, 2021). "We therefore sought to determine whether the upregulated expression of CD84 on cells in the tumor microenvironment is modulated by MIF." (PMID 33465053, 2021). "In sum, tumor cells and tumor-associated macrophages might contribute to angiogenic factor expression but stabilized MIF in epithelial tumor cells provides the prerequisite for both scenarios." (PMID 33542244, 2021). "In addition, IHC staining for CD138 and MIF were performed in BM and spleen samples from tumor-bearing mice." (PMID 34268123, 2021). "CXCR4/MIF axis positively modulates tumor growth and EMT interaction in NSCLC." (PMID 33314730, 2021). "Importantly, in our sporadic CRC model, MIF as a tumor-promoting factor is selectively targetable in tumor cells by inhibiting Hsp90, supporting a strong rationale for MIF as a potential therapeutic target in sporadic CRC." (PMID 33542244, 2021). "Furthermore, MIF affects the tumor microenvironment facilitating proliferation and growth through promotion of angiogenesis necessary for maintaining tumor growth." (PMID 34157052, 2021). "Inhibition of MIF signaling can restore anticancer immune responses in tumor microenvironments." (PMID 34389619, 2021). "MIF also contributes to TAM polarization to the M2 subtype in tumor-bearing mice." (PMID 34407796, 2021). "MiR‐608 mitigates tumor migration and invasion via directly targeting MIF in LUAD." (PMID 33314730, 2021). "In contrast to LPS (where no common cytokine could be identified activated in tumor cells line), Nigericin treatment revealed MIF as the most consistently upregulated cytokine in tumor cells, except for MCF7 cells." (PMID 33613529, 2020). "In addition to inflammatory and immunologic functions, MIF plays a role in tumor cell growth, cell proliferation, wound repair, regulation of cytochrome c release, and inhibition of Bim-induced apoptosis." (PMID 33520998, 2020). "Cytokines are a family of soluble factors, classified into growth factors, chemokines, angiogenic factors and interferons and involved in tumor immune-landscape, by exerting pro- (IL-1β, IL-6, IL-8, and macrophage migration inhibitory factor—MIF) and anti-inflammatory (IL-10 and TGF-β) functions." (PMID 32012917, 2020). "NB culture-derived MIF was also shown to activate tumor cell migration." (PMID 32155795, 2020). "Generally speaking, during early tumor initiation and outgrowth, MIF supports pro-inflammatory immune phenotypes governed by early infiltrating or resident macrophages and inflammatory IL-17 producing T lymphocytes that, collectively, increase inflammation and, likely, cell and tissue damage." (PMID 33324425, 2020). "Since MIF has been directly implicated in the regulation of endothelial differentiation, we believe that MIF as a tumor promoter proves again that monocytes-derived ECs can be a subpopulation of M2-TAMs, reaching the tumor to favor angiogenesis by also making part of the blood vessel structures." (PMID 31906296, 2020).
tumor (continued). "MIF production is triggered by an autocrine signal emitted by tumor cells and stimulates the production of cytokines, chemokines, and growth, as well as angiogenic factors that lead to tumor growth, increasing its aggressiveness and metastatic potential." (PMID 32963755, 2020). "Immunization with MIF KO AGN2a cells significantly increased protection against tumor as compared with immunization with wild-type AGN2a cells, increasing the proportions of tumor-specific cytotoxic T cells." (PMID 32155795, 2020). "Similarly, MIF, which is a pleiotropic cytokine frequently overexpressed in many cancer types, is able to promote tumor growth and progression by protecting cancer cells from ICD." (PMID 32854690, 2020). "Interestingly, complete tumor rejection was observed in a subset of MIF−/− mice that coincided with significant decreases in Tregs and corresponding increases in splenic CD4+ and CD8+ lymphocytes." (PMID 33324425, 2020). "We currently envision that tumor CD74 functions in antigen presentation to the immune cells in the tumor microenvironment rather than acting as a receptor for an inflammatory protein MIF." (PMID 33327409, 2020). "Given that MIF functionally regulates the infiltration, expansion, and immune-suppressive phenotypes of such a variety of immune cell subtypes that collectively govern tumor immunity, further translational studies will be exceptionally informative." (PMID 33324425, 2020). "Taken as a whole, these data seem to indicate that the MIF possesses both pro and antioncogenic activities that may depend on the phenotype and site of the tumor and possibly the genetic background of the patients and other yet unidentified cofactors." (PMID 32155795, 2020). "Interestingly, an oxidized isoform of MIF was identified as a prognostic biomarker and therapeutic target in inflammatory disease and cancer, showing again that the pro-oxidative tumor microenvironment is playing a role in angiogenesis." (PMID 31906296, 2020). "It was proposed that overproduction of MIF from NB cells provokes activation-induced T-cell death through an IFN-gamma pathway that may eliminate activated T cells from the tumor microenvironment and thus contribute to escape from immune surveillance." (PMID 32155795, 2020). "It is presently unclear why different syngeneic tumor cell lines have differential tumor cell MIF requirements but it seems plausible that endogenous, autocrine acting myeloid cell MIF and paracrine acting tumor cell MIF are both capable of promoting MDSC differentiation and immune suppression." (PMID 33324425, 2020). "The current studies agree that MIF is upregulated in NB tumor tissues and cell lines and that it may be involved in NB aggressiveness and immune-escape." (PMID 32155795, 2020). "Moreover, significantly reduced lung metastases were observed in mice bearing MIF-sh1 tumors than scr tumor bearing group." (PMID 32943608, 2020). "Some studies have shown that MIF can promote tumor growth and other diseases." (PMID 33148606, 2020). "Our data demonstrate that MIF production could be involved in NLRP3 activation in tumor cells treated with Nigericin." (PMID 33613529, 2020). "Since the blockade of two NF-kB and JNK II-dependent factors, such as extracellular matrix metalloproteinase inducer (EMMPRIN) and macrophage migration inhibitory factor (MIF), reduced the invasiveness of the tumor cell lines, the authors suggested their involvement in this context." (PMID 32354198, 2020). "Our data strongly suggest that MIF plays a key role in tumor growth and metastasis of TNBC." (PMID 32943608, 2020). "Overexpression of MIF by cancer cells is known to promote tumor growth through multiple mechanisms." (PMID 31664114, 2019).
tumor (continued). "Altogether, these data demonstrate that both tumor cell-derived MIF and circulating MIF could play major local and systemic roles in angiogenesis promotion, respectively." (PMID 31013837, 2019). "Indeed, MIF is involved in cancer progression through different pathways leading to cell proliferation, cell invasion, angiogenesis and tumor immune escape." (PMID 30634708, 2019). "The number of macrophages in the tumor margin of MIF-deficient mice was similar to that of healthy mice, showing that the resident macrophages are not affected by the lack of MIF but migration is decreased in the knockout mice." (PMID 31360118, 2019). "MIF distribution can help us identify the role of MIF in tumor development." (PMID 31360118, 2019). "MIF is known to induce tumor angiogenesis in different cancers." (PMID 31664114, 2019). "The hazard ratio was 2.4 (1.74–3.31) for patients with MIF positive tumor tissue." (PMID 30814573, 2019). "Greater tumor burdens were observed in MIF−/− mice than in WT mice." (PMID 31360118, 2019). "However, in the tumor microenvironment, the MIF-inhibitory mechanism is released owing to higher chemerin concentrations in CAMs, increasing the capacity for recruiting MSCs to the tumor microenvironment." (PMID 31561459, 2019). "Moreover, tumor expression and/or circulating plasma levels of MIF have been proposed as biomarkers of prognosis and therapeutic response." (PMID 31635049, 2019). "Regarding the modulation of angiogenesis by MIF, targeting this factor could be effective in slowing down tumor development by reducing the blood supply to the primary lesion, and then reducing metastasis development." (PMID 31013837, 2019). "In this line, it has been shown that MIF is necessary for antigen sampling and transport from the gut to the lymph nodes, which may decrease the capacity of our MIF−/− mice to control tumor development." (PMID 31360118, 2019). "Moreover, the differential histological characterization showed a different growth path and rate dependent on MIF, denoting its influence in modeling the tumor microenvironment." (PMID 31360118, 2019). "Natural killer (NK) cells cannot attack the tumor due to the high amount of HLA expressed on UM cells, which inhibits their function, and due to the presence of high levels of macrophage migration inhibitory factor (MIF) and TGF-β in the aqueous humor, which inhibit NK cell function." (PMID 31394807, 2019). "MIF staining was specific to the tumor cell membrane, as well as cytoplasm." (PMID 30814573, 2019). "We found significantly fewer macrophages in the tumors of MIF-deficient mice than in those of WT mice by flow cytometry and immunohistochemical analysis; these differences were found in the tumor stroma but not in the tumor margin." (PMID 31360118, 2019). "In addition to IL‐8, we also found that expression of the chemokines MIF and IL‐10, which have been shown to mediate tumour‐promoting crosstalk between tumours and the tumour microenvironment, was increased following ZNF143 knockdown." (PMID 30933430, 2019). "We present evidence supporting a model in which depletion of MIF expression in the primary tumor in vivo leads to a robust anti-tumor immune response marked by enhanced DC maturation, followed by increased IFNgamma-producing T cells in the tumor." (PMID 29864117, 2018). "A number of studies suggest that MIF may be involved in processes regulating cell proliferation, tumor angiogenesis, and metastasis through activation of STAT3, ERK, and phosphatidylinositide 3‐kinase/AKT pathways." (PMID 29896883, 2018). "Furthermore, we found that MIF depletion from the tumor cells resulted in greater numbers of activated intra-tumoral dendritic cells (DCs)." (PMID 29864117, 2018). "Similarly to 5-FU, targeting tumor-derived MIF prolonged survival to tumor-bearing animals and increased the cytotoxic T cell response within the tumor." (PMID 29707160, 2018).
tumor (continued). "This highlights an intriguing role of endogenous MIF as important inhibitory checkpoint in oncogenesis as tumor-derived CD4+ Tregs play an important prooncogenic role by suppressing the immune response to tumor cells." (PMID 29707160, 2018). "This relieved the activity of MIF and enhanced macrophage recruitment to promote tumor growth." (PMID 29618368, 2018). "Importantly, MIF overexpression in the serum of cancer patients and in tumor biopsies has been correlated with enhanced tumor progression and metastasis." (PMID 29864117, 2018). "In addition, we have previously published that MIF expression in the primary tumor leads to an increased abundance of intratumoral monocytic myeloid-derived suppressor cells (MDSCs), contributing to establishment of an immunosuppressive microenvironment." (PMID 29864117, 2018). "Several previously published studies also strongly link MIF expression to dampened anti-tumor immune responses in cancer, which may be indirect evidence of the suppression of ICD." (PMID 29864117, 2018). "This suggests that MIF may be involved in two distinct mechanisms leading to immunosuppression in the tumor microenvironment depending on the time of tumor growth." (PMID 29864117, 2018). "In this model, MIF secretion by H2052/484 tumor cells may attract immunosuppressive cells such as MDSC and polarized macrophages toward an immunosuppressive M2 phenotype, thus promoting tumor growth." (PMID 29949929, 2018). "We next hypothesized that the increased T cell abundance and activation in MIF KD tumors is due to enhanced activation of dendritic cells (DCs) either in the draining lymph nodes or the tumor." (PMID 29864117, 2018). "CD74 triggering by autocrine MIF may then enhance their ability to proliferate, as shown for tumor cells 39, and produce proinflammatory cytokines to mediate CNS pathology in MS." (PMID 30160778, 2018). "Hence, MIF seems to favor tumor growth by increasing Treg generation, through the modulation of IL-2 production." (PMID 29707160, 2018). "The average time to tumor occurrence was significantly delayed in MIF KO mice." (PMID 29864117, 2018). "Supporting this, we demonstrated that loss of MIF expression in the primary tumor led to an increased abundance of intra-tumoral IFNgamma-producing CD4+ and CD8+ T cells, and that depletion of T cells from mice bearing MIF-deficient tumors restored growth to the level of MIF-expressing tumors." (PMID 29864117, 2018). "Finally, when exogenously-administered to tumor-bearing MIF(-/-) animals, IL-2 restored the generation of Tregs and tumor growth." (PMID 29707160, 2018). "When comparing age-matched 8-week-old mice, the point at which about half of the mice in our studies presented with at least one palpable tumor mass, MIF KO mice showed significantly fewer tumors per mouse and, in fat pads that did not yet harbor detectable tumors, smaller fat pads by weight." (PMID 29864117, 2018). "Interestingly, both populations of tumor-infiltrating T cells in the MIF KD tumors were more activated, as exhibited by the ability of both CD8+ and CD4+ T cells to express IFNgamma after ex vivo re-stimulation." (PMID 29864117, 2018). "MIF also inhibits the lysing of tumor cells by natural killer (NK) cells." (PMID 29707160, 2018). "In contrast, pharmacological intervention/inhibition of MIF diminishes MDSC buildup in the tumor." (PMID 29247872, 2017).